IL11 (interleukin 11)
Diseases named in the same sentence as IL11 in open-access papers (continued):
Sharing a sentence is not in itself a finding about the gene and the disease.
tumor (continued). "Interestingly, microglia isolated from HRasV12+ larval brains showed increased expression levels of il4 and il11 (not shown), suggesting the generation of an anti‐inflammatory state during tumor initiating stages." (PMID 35194846, 2022). "In addition, studies of IL-1β, IL-11, IL-17, IL-18, and TNF also indicate that proinflammatory cytokines are key regulators for TME in inhibiting tumor cell proliferation, reducing inflammation, and preventing tumor metastasis." (PMID 35069767, 2022). "In addition to IL-6, HMC3 microglia also secreted detectable amounts of LIF and IL-11, suggesting that IL-6, LIF, and IL-11 may contribute to paracrine signaling in the MB tumor microenvironment." (PMID 35159191, 2022). "However, the expression of STAT3-target genes Il11 and Socs3 was similar among gp130F/F:Nlrp3-/- and gp130F/F tumor and matched non-tumor gastric tissues at 3 and 6 months of age." (PMID 35299732, 2022). "Mechanistically, it has been proposed that this link would be due, at least partially, to the decrease of the tumor suppressor microRNA-30c (miR-30c), which prevents tumor chemotherapy resistance by directly reducing twinfilin 1 (TWF1) levels and its secondary target, secreted IL-11." (PMID 35163731, 2022). "Immune factors, including cytokines (such as interleukin-11 (IL-11), and interleukin-6 (IL-6)) and chemokines (including IL-6, CCL5, and CXCL10), play a role in converting normal fibroblasts into CAFs, and some of these immune factors act in a feedback loop between the CAFs and the tumor." (PMID 35300411, 2022). "Taken together with the reports that IL-11 binds to its receptors on osteoclasts or their precursors to regulate the formation and function of osteoclasts, these findings suggest that the Ac-KLF5/CXCR4 axis in tumor cells induces osteoclast differentiation by increasing IL-11 secretion." (PMID 33731701, 2021). "Although the expression of Il11 was elevated in tumor tissues compared with non-tumor tissues, the Egfp expression that can represent Il11 expression in BM-derived cells was not elevated in either tumor tissues or non-tumor tissues from Il11-Egfp BM chimeric mice." (PMID 33863879, 2021). "In line with the systemic effects of senescence observed in cancer patients, SASP factors including IL‐11 and angiopoietin‐like 4 were detected in the plasma of mice engrafted with HER2‐driven senescent tumour cells, contributing to larger metastases from proliferating tumour cells." (PMID 32981205, 2021). "We isolated tumor and nontumor tissues and examined Il11 mRNA expression using qPCR." (PMID 33863879, 2021). "We identified some key genes via the PPI and ceRNA networks and that the expression of IL-11 was upregulated whereas that of miRNA and LINC00261 was downregulated; moreover, the model was positively correlated with the infiltration of several subtypes of tumor-infiltrating immune cells." (PMID 32158466, 2020). "For instance, IL-6, IL-17, and IL-11 may increase the proliferation of tumor cells, under conditions, such as chronic hypoxia, lack of nutrients, or insufficiency of anti-tumor immunity." (PMID 32973519, 2020). "IL-6 and IL-11 activate signal transducer and activator of transcription 3 (STAT3), and this canonical pathway may represent a mechanism by which chronic inflammation contributes to tumour initiation and progression." (PMID 31123345, 2019). "Indeed, TGF-β may for instance promote IL-11 secretion by CAFs, which in turn activates STAT3 and drives the proliferation of tumor cells." (PMID 27148488, 2016). "These pro-tumorigenic cytokines include interleukin (IL)-6, IL-11, IL-21 and IL-22 that activate the STAT3 transcription factor; TNFα, IL-1 and IL-18 that activate NF-κB; and the IL-23 to IL-17 axis of inflammation that activates both STAT3 and NF-κB in tumor cells." (PMID 31051015, 2016).
tumor (continued). "Although we have to investigate whether IL-11 from tumours directly affect the generation of MDSCs or not, we speculate that MDSCs were induced by IL-11 from the local tumour microenvironment, which was related with the immunosuppression at tumour sites." (PMID 28781374, 2015). "Together these results demonstrate that halofuginone both decreased tumor-induced bone osteolysis and promoted tumor-induced bone formation, and suggest that these effects are partly due to the ability of halofuginone to reduce the expression of RANKL and IL-11 by tumors cells." (PMID 26015407, 2015). "Given the importance of IL-11 in promoting tumour initiation and development, and IL-6 in facilitating local polymorphonuclear infiltration in the gp130757FF mouse, it is significant that WP1066 effectively reduced the expression levels of both cytokines coincident with reversal of tumour growth." (PMID 24804649, 2014). "IL11 immunostaining was significantly higher in epithelial tumour cells from Grades 1 and 3 but not Grade 2 tissue compared to endometrial epithelial cells from proliferative phase women (p < 0.05 in G1 and p < 0.001 in G3) but was higher only in Grade 1 compared to postmenopausal women." (PMID 20553623, 2010). "STAT3 activation and subsequent tumor development do not occur without the Glycoprotein 130 (gp130) receptor, which is a signaling element of the IL-6R‒gp130 complex, and the IL-6 family member IL-11 is a promotion element of GC by activating STAT3 to overexpress proliferative genes in mice." (PMID 40264171, 2025). "For instance, elevated IL11 expression may suppress anti-tumor immune activity by fostering the development of an immunosuppressive microenvironment, while increased ERBB3 expression may impact immunotherapy outcomes by modulating the interplay between tumor cells and immune cells." (PMID 40708839, 2025). "Importantly, the tumor cells could significantly produce not only the ILs such as IL-6, IL-8, and IL-11, required for osteoclastogenesis, but also strengthen the expression of CXCR4 and CXCR7, establishing a “fertile soil” that accelerates tumor cells to adhere to bone matrix and thrive in bone." (PMID 36046435, 2021). "Moreover, reciprocal BM transfer experiments revealed that Il11 expression in non-hematopoietic cells might be primarily responsible for the increased tumor numbers and tumor load in the colon." (PMID 33863879, 2021). "We observed that tumour cells activate the STAT3 and STAT1 signalling pathways, but not the PI3K–AKT or MAPK pathways, after the IL‐11 challenge." (PMID 40673604, 2025). "Consistent with MAFF knockdown, we observed that inhibition of BACH1, IL11, or STAT3 did not change primary tumor growth, suggesting that their main role in cancer was not the regulation of cell proliferation in our experimental settings." (PMID 34262028, 2021). "In the orthotopic mouse model, we also confirm that overexpression of IL11 restores the levels of tumor metastasis and expression of phospho-STAT3 expression in the absence of MAFF, supporting a critical role of IL11 in MAFF-mediated tumor metastasis." (PMID 34262028, 2021). "We previously demonstrated that exogenous IL11 phosphorylates STAT3, but not ERK, or AKT in Ishikawa, HEC1A and AN3CA cells in vitro and Ishikawa and HEC1A xenograft tumours in vivo, confirming that IL11 likely does not act via these pathways in these cells." (PMID 28186993, 2017). "Here we have demonstrated that IL-1RT1−/− signaling is not required for IL-11/STAT3 mediated pathology, with genetic depletion of IL-1RT1−/− resulting in a more severe tumor phenotype by promoting an anti-inflammatory, pro-tumorigenic environment." (PMID 25528766, 2015). "Consistently, tumor proliferation, apoptosis, and STAT3 phosphorylation, as well as gene expression of Ereg, IL-6, and IL-11, were not significantly altered in Villin:Cre-Phd2fl/fl mice as compared with the controls." (PMID 36509284, 2022).
tumor (continued). "TGF-β also stimulates the secretion of interleukin (IL)-11 by CAFs, which then acts on colorectal cancer cells activating the gp130/STAT3 signalling pathway, which is required for tumour initiation but it is not important for the growth of tumours once established." (PMID 29701666, 2018). "IL11Rα Ab treatment did not alter IL11 mRNA, but led to a trend in increased GP130 mRNA, while IL11Rα Ab and doxorubicin treatment significantly increased IL11Rα (p < 0.05) in subcutaneous AN3CA tumours." (PMID 28186993, 2017). "While VEGF and IL-11 secretion by MDA-MB231 cells were not affected by the scaffold type and PTHrP was secreted at undetectable levels (<0.3 pM) from either mineralized or non-mineralized tumor models (data not shown), IL-8 secretion was increased by 38% in mineralized scaffolds HA." (PMID 20107512, 2010).
cancer (211 papers, 2008 to 2026). A tumor composed of atypical neoplastic, often pleomorphic cells that invade other tissues. "For in vivo assessment of cancer cells growth linked to IL‐11 activity, we established subcutaneous xenografts of A549 and H1975 cells knocked down for IL‐11RA." (PMID 40673604, 2025). "In CNS disease and cancer immunotherapy, modulation of IL11 pathways has been linked to improvements in the immune microenvironment and cytokine storm suppression, offering translational opportunities." (PMID 41487426, 2025). "At the transcriptomic level, we found that CCL19 and TRAF3IP3 were protective factors in pan‐cancer, whereas IL11, PTGES, and TNFAIP3 were risk factors." (PMID 40714831, 2025). "For example, the cancer-associated fibroblasts treated with cisplatin simulated IL-11 upregulated and subsequently activated STAT3, which finally promotes the lung adenocarcinoma cell resistance to cisplatin." (PMID 38245798, 2024). "Recent studies have demonstrated that STAT3 signaling axis activation through IL-11 production by cancer-associated fibroblasts and myeloid cells is more potent for gastrointestinal tumor progression than IL-6." (PMID 38892375, 2024). "IL‐11 has also been implicated in fibrotic remodeling that affects cancer‐associated fibroblasts as well as lung, liver, and heart fibrosis." (PMID 38023717, 2023). "In several studies, IL11 has been associated with trophoblast migration and invasion, the mechanisms of which are similar to those involved in cancer progression." (PMID 36982551, 2023). "Increased IL‐11 signaling has been associated with cancer proliferation, metastasis, and chemoresistance, leading to the progression of gastric, colorectal, breast, and bone cancers among others." (PMID 38023717, 2023). "IL-11 has also been particularly linked to poor prognosis in cancers that possess epithelial traits." (PMID 35326569, 2022). "For example, elevated expression has been linked to several cancers, including GC, where IL-11 levels are elevated in preclinical models of GC." (PMID 35844493, 2022). "Elevated IL-11 expression has been associated to various human cancers of both epithelial and hematopoietic origin." (PMID 34201209, 2021). "Recently, there have been reports that overexpression of IL-11 is associated with a variety of cancers." (PMID 34360848, 2021). "IL-11 is secreted not only from different types of cancer cells but also from cancer-associated cells, including cancer-associated fibroblasts and myeloid cells." (PMID 34201209, 2021). "Through genetic remodeling and m6A-mRNA profiling, we link YTHDF2 deficiency to mRNA stabilization of IL-11 and Serpin E2, the key mediators in support of hypoxia-induced cancer cell survival and vascular reconstruction." (PMID 31735169, 2019). "Secretion of IL-11 by cancer-associated fibroblasts (CAF) promotes cancer cell metastasis in colorectal cancers." (PMID 27922075, 2016). "In addition to the upregulated Il11 and Il1rn, which were notably lowly transcribed in early passage deermouse cells in comparison to mouse cells, two cancer-associated genes, Brca1 and Myc, were more highly transcribed in P47 than in P4 cells." (PMID 41262241, 2025). "Similarly, IL-6/IL-11 signaling in cancer-associated fibroblasts (CAFs) induces STAT3 activation, creating a protumorigenic niche that drives CRC growth and correlates with dismal outcomes." (PMID 40963625, 2025). "Notably, TGF-β1 is a potent inducer of IL-11 expression in stromal, epithelial, and cancer cells, and IL-11 has been implicated as a biomarker in various cancers and fibrotic diseases." (PMID 40497943, 2025). "STAT activation by IL-11 in cancer-associated fibroblasts often indicates a poor prognosis." (PMID 38892375, 2024).
cancer (continued). "The signalling pathways underlying IL11 effects in cancer were mostly thought JAK/STAT3 related but, based on more recent data, MEK/ERK and — in particular — LKB1/AMPK/mTOR signalling, may now feature." (PMID 38054591, 2023). "Patients with PJS have an increased risk of cancer and it is interesting to speculate that IL11-mediated activation of wildtype LKB1, on top of the germline, PJS-causing LKB1 LOF mutation, plays a role in cancer risk in these patients." (PMID 38054591, 2023). "Moreover, IL-6/IL-11 activates STAT3 in cancer-associated fibroblasts (CAFs) to promote CRC progression and poor prognosis." (PMID 35783510, 2022). "Similarly, IL11 activity in hepatic with pancreatic stellate cells seems pro-inflammatory, and IL11 activity in cancer-associated fibroblasts is linked with an inflammatory response." (PMID 36012165, 2022). "Moreover, STAT3 activation through IL-6/IL-11 in cancer associated fibroblasts (CAFs) promoted CRC development and poor prognosis." (PMID 34046355, 2021). "Similarly, high levels of CCL17 and IL-11 are associated with poor outcome in malignant neoplasms due to aggressive biological behavior regarding local invasion and metastasis." (PMID 32793466, 2020). "HGF and IL-11 are anti-inflammatory cytokines; in addition, IL-11 promotes bone destruction by osteoclasts and inhibits bone formation by osteoblasts, thus causing cancer-induced bone lesions." (PMID 29098000, 2017). "In keeping with this concept, transcripts encoding IL-6 and IL-11, key cytokines involved in inflammation-associated Stat3 activation in cancer, were marginally elevated after one week of GLI2A expression but highly induced by 2 and 3 weeks, when Stat3 activation is widespread." (PMID 26859571, 2016). "Furthermore, According to evidence, LIM domain only two overexpression in prostate stromal cells, particularly peripheral zone derived stromal cells and cancer-associated fibroblasts (CAFs), may block miR-204-5p, which causes IL-11 to be upregulated." (PMID 38745115, 2024). "However, we also noticed that blockade of IL-11 can only partially reverse the downregulated expression of GPR84 caused by cancer CM, implying that some other unknown components in CM inhibited the level of GPR84, which should be further investigated." (PMID 36593458, 2023). "In addition to circRNA, interleukin-11 (IL-11), secreted by cancer-associated fibroblasts, previously treated with cisplatin, also induced a significantly higher viability of A549 cells following cisplatin exposure by activating the IL-11R/STAT3 anti-apoptotic signaling pathway." (PMID 38003688, 2023). "To further investigate the role of IL‐11 in helping cancer cells resist NK cell‐mediated killing, we overexpressed IL‐11 in 231‐GFP cells." (PMID 41178513, 2026). "Blocking IL‐11 trans‐signaling has the potential to promote the proliferation of NK cells and enhance their killing ability against cancer cells." (PMID 41178513, 2026). "A similar scenario exists in gastric cancer, where IL‐6 controls activities linked to angiogenesis, cancer inflammation and tissue remodeling, and IL‐11 instructs cancer cell survival and proliferation." (PMID 39673075, 2025). "Within the constructed network, MMP1, KRT7, EGR1, and IL11 played crucial roles, likely due to the cell lines representing invasive and proliferative cancers." (PMID 41590789, 2025). "Cytokines such as IL-1, IL-6, TNF, and others (TGF-β, IL-22, IL-11) interact with cancer cells, promoting signaling pathways (e.g., IKK-NF-κB, JAK-STAT3, MAPK-AP1) that support cancer progression." (PMID 39996799, 2025). "In the NRF2 addiction cancer model, IL-11 disruption significantly suppressed carcinogenesis, implying that IL-11 plays an essential role in NRF2-driven tumorigenesis." (PMID 40584290, 2025). "The results from the same team show that IL-11 activates mTOR signaling and identify that the IL-11/mTOR axis acts as a signaling commonality in stromal, epithelial, and cancer cells." (PMID 40092733, 2025).